H3-5 (H3.5 histone)
Description:
Core component of nucleosome. Nucleosomes wrap and compact DNA into chromatin, limiting DNA accessibility to the cellular machineries which require DNA as a template. Histones thereby play a central role in transcription regulation, DNA repair, DNA replication and chromosomal stability. DNA accessibility is regulated via a complex set of post-translational modifications of histones, also called histone code, and nucleosome remodeling. Hominid-specific H3.5/H3F3C preferentially colocalizes with euchromatin, and it is associated with actively transcribed genes.
Synonyms: H3F3C; H3.5; H3.3C
Tractability: Small molecule: a structure with a bound ligand is known. PROTAC: UniProt records ubiquitination sites on it; ubiquitination databases record sites on it.
Gene: Protein-coding gene on chromosome 12 (31,791,185 to 31,792,298, reverse strand). Ensembl gene ENSG00000188375.
Subcellular location: Nucleus; Chromosome
Subcellular location (Human Protein Atlas): Nucleoplasm
Gene Ontology:
Molecular function: nucleosomal DNA binding; protein binding; structural constituent of chromatin; DNA binding; protein heterodimerization activity
Biological process: positive regulation of cell growth; heterochromatin formation; kinetochore assembly; mitotic metaphase chromosome alignment
Cellular component: euchromatin; nucleoplasm; kinetochore; nucleosome; chromosome; nucleus
Genetic constraint (gnomAD): Loss-of-function variants: 9 observed, 8.94 expected, observed/expected ratio (o/e) 1.01, 90% interval 0.6 to 1.69. That is too few expected variants to judge how well the gene tolerates losing a copy. Missense variants: 173 observed, 188.57 expected, observed/expected ratio (o/e) 0.92, 90% interval 0.81 to 1.04. Synonymous variants: 82 observed, 76.96 expected, observed/expected ratio (o/e) 1.07, 90% interval 0.89 to 1.28.
Homologues: Orthologues: chimpanzee H3-3A (96% identical), Caenorhabditis elegans his-71 (96% identical), rat H3f3c (96% identical), rat H3f3bl2 (94% identical), rat H3f3al3 (80% identical). Paralogues in human: H3-3A (96% identical), H3-3B (96% identical), H3C13 (87% identical), H3C14 (87% identical), H3C15 (87% identical), H3C1 (86% identical), H3C10 (86% identical), H3C11 (86% identical), H3C12 (86% identical), H3C2 (86% identical), H3C3 (86% identical), H3C4 (86% identical), and 8 more.
Diseases named in the same sentence as H3-5 in open-access papers:
H3-5 is named in the same sentence as 4 diseases in open-access papers, as found by Europe PMC text mining. Sharing a sentence is not in itself a finding about the gene and the disease. The quoted sentences say what the papers report.
cancer (2 papers, 2015 to 2025). A tumor composed of atypical neoplastic, often pleomorphic cells that invade other tissues. "The neutrophil degranulation complex was defined by the terms antimicrobial peptides (R-HAS-6803157), neutrophil degranulation (R-HSA-6798695), response to yeast (GO:0001878), and transcriptional misregulation in cancer (KEGG:05202); it included the proteins ELANE, H3-5, MPO, LYZ, and PRTN3." (PMID 39997396, 2025).
H3-5 also shares sentences with these, for which no sentence is quoted: systemic lupus erythematosus (2 papers); brain tumors (1); seminoma (1).